SMS (spermine synthase)
Diseases named in the same sentence as SMS in open-access papers (continued):
Sharing a sentence is not in itself a finding about the gene and the disease.
lung adenocarcinoma (2 papers, 2023 to 2024). A carcinoma that arises from the lung and is characterized by the presence of malignant glandular epithelial cells. "First, we identified two central genes, CPS1 and SMS, that affect the prognosis of lung adenocarcinoma by stepwise multivariate Cox analysis and constructed a prognostic model associated with Arg and Pro metabolism." (PMID 37709932, 2023). "First, in the GSE46539 lung adenocarcinoma cohort, the expression level of PSMC6, SMOX, and SMS was higher in the tumor samples than in the normal samples, which was consistent with the previous result in TCGA lung cancer samples." (PMID 38650895, 2024). "First, we compared the difference in mRNA expression between normal and tumor groups in lung adenocarcinoma with CPS1 and SMS genes in the TCGA and GEPIA2 databases, and also validated them in the GEO database, and analyzed the protein expression level of data from CPTAC in the UALCAN database." (PMID 37709932, 2023).
triple-negative breast carcinoma (2 papers, 2021 to 2022). An invasive breast carcinoma which is negative for expression of estrogen receptor (ER), progesterone receptor (PR), and human epidermal growth factor receptor 2 (HER2). "High SMS mRNA expression was related to poor survival and increased risk of metastasis in triple-negative breast cancer." (PMID 33494814, 2021). "In plasma of patients with triple-negative breast cancer, high mRNA expression of SMS is highly related to metastasis and poor prognosis, which is similar to our results." (PMID 35804447, 2022).
Anxiety (1 paper, 2023). Intense feelings of nervousness, tension, or panic often arise in response to interpersonal stresses. "However, a 22-year longitudinal study of 1255 Canadian individuals showed that the N1-acetyltransferase (SAT1) and SAT1, spermine synthase (SMS) polymorphisms are associated with anxiety and suicide attempts." (PMID 38069051, 2023).
anxiety disorder (1 paper, 2010). A category of psychiatric disorders which are characterized by anxious feelings or fear often accompanied by physical symptoms associated with anxiety. "In this study, SMS, which is involved in spermine biosynthesis, demonstrated strong associations with anxiety disorders through both main genetic effects as well as through a gene-gene interaction with SAT1." (PMID 21152090, 2010). "Two SAT1 and five SMS SNPs exhibited recessive modes of inheritance regarding the prediction of anxiety disorders, while three SMS SNPs were significant in the dominant model." (PMID 21152090, 2010). "In addition to the main genetic effects, we identified a gene-gene interaction between SMS and SAT1 in conferring risk for anxiety disorders." (PMID 21152090, 2010).
atherosclerosis (1 paper, 2021). A disease characterized by the build-up of fatty material and calcium deposition in the arterial wall resulting in partial or complete occlusion of the arterial lumen. "Studies on KO mice for LDL-R, in which the bone marrow of KO mice for the enzyme sphingomielin synthase 1 (SMS) was transplanted, showed a reduction in atherosclerosis at the level of the aorta." (PMID 34944757, 2021).
chlamydial infection (1 paper, 2022). "The ceramide is converted to sphingomyelin (SM) by a chlamydial infection-dependent SM synthesis (cidSM-synthesis) pathway, which occurs even in the absence of the SM synthases (SMS)-1 and -2 of host cells." (PMID 36499025, 2022).
deafness (1 paper, 2011). An inherited or acquired condition characterized by the complete loss of the ability to hear from one or both ears. "However, deafness and endolymphatic hydrops due to the PhexHyp-Duk mutation exhibit background-dependent variable expression; and in the Gy, alteration of the spermine synthase gene, rather than Phex, is responsible for inner ear defects." (PMID 21854633, 2011).
Elejalde syndrome (1 paper, 2019). "To investigate a possible correlation between depletion of MyoVa protein and SMS transcription, we also evaluated the expression of SMS in MYO5A-null primary fibroblasts isolated from patients with Griscelli Syndrome Type 1/Elejalde syndrome." (PMID 30733278, 2019).
endometrial cancer (1 paper, 2017). Primary or metastatic malignant neoplasm involving the endometrium (mucous membrane that lines the endometrial cavity). "Future studies should explore the role of SAT1, SMS and SRM in the polyamine addiction of endometrial cancer, in particular the mechanisms that cause some of these to be more DFMO sensitive than others." (PMID 29240775, 2017).
epilepsy (1 paper, 2024). A brain disorder characterized by episodes of abnormally increased neuronal discharge resulting in transient episodes of sensory or motor neurological dysfunction, or psychic dysfunction. "Among the triplosensitive genes located in the duplicated region, ARX, CDKL5, CNKSR2, MID1, PTCHD1, RPS6KA3, and SMS are known to be involved in intellectual developmental disorders with/without epilepsy." (PMID 39062680, 2024).
Epileptic encephalopathy (1 paper, 2018). A condition in which epileptiform abnormalities are believed to contribute to the progressive disturbance in cerebral function. "From a cohort of patients with epileptic encephalopathy, we identified two patients with mutations in the spermine synthase (SMS) gene, causing Snyder–Robinson syndrome (SRS)." (PMID 29536202, 2018).
Failure to thrive (1 paper, 2024). Failure to thrive (FTT) refers to a child whose physical growth is substantially below the norm. "The lack of SMS protein in the G56S mice resulted in increased spermidine/spermine ratio, failure to thrive, short stature and reduced bone density." (PMID 38463005, 2024).
hearing loss (1 paper, 2019). "Potential contributions of PHEX and FGF23 to hearing loss were confounded because both mutations extended beyond the Phex coding region, and Gy mutations affected the nearby SmS gene, which has been associated with hearing loss." (PMID 30808384, 2019).
Huntington disease (1 paper, 2019). Huntington disease (HD) is a rare neurodegenerative disorder of the central nervous system characterized by unwanted choreatic movements, behavioral and psychiatric disturbances and dementia. "Moreover, MYO5A and SMS are up-regulated in differentiated neurons and the proteins they encode are less abundant in human brains with Huntington’s disease, a progressive neurodegenerative disorder." (PMID 30733278, 2019).
latent infection (1 paper, 2022). "We observed multiple genes in polyamine pathway, including ODC1, SRM, SMS and DHPS, were significantly dysregulated due to KSHV latent infection." (PMID 35486659, 2022).
leukemia (1 paper, 2020). A malignant (clonal) hematologic disorder, involving hematopoietic stem cells and characterized by the presence of primitive or atypical myeloid or lymphoid cells in the bone marrow and the blood. "The SMS inhibitor showed a strong inhibitory effect on the growth of P388 leukemia cells." (PMID 32411183, 2020).
melanoma (1 paper, 2019). A malignant, usually aggressive tumor composed of atypical, neoplastic melanocytes. "Accordingly, various human melanoma cells displayed a SL metabolism signature associated with (i) a robust and a low expression of UGCG and SGMS1/2, respectively, (ii) higher in situ enzyme activity of GCS than SMS, and (iii) higher intracellular levels of GlcCer than SM." (PMID 31114500, 2019).
pulmonary hypertension (1 paper, 2022). Increased pressure within the pulmonary circulation due to lung or heart disorder. "Spermine synthase inhibition inhibited platelet-derived growth factor-BB-mediated PASMC proliferation in vitro and reduced monocrotaline-induced pulmonary hypertension in rats in vivo." (PMID 36093148, 2022).
Snyder Robinson mental retardation syndrome (1 paper, 2019). "Mutations in the spermine synthase gene areassociated with Snyder Robinson mental retardation syndrome." (PMID 30967493, 2019). "This interaction betweenmyosin Va and spermine synthase may have other implications for both Griscellisyndrome type 1 and Snyder-Robinson mental retardation syndrome." (PMID 30967493, 2019).
tauopathy (1 paper, 2024). Neurodegenerative disorders involving deposition of abnormal tau protein isoforms (tau proteins) in neurons and glial cells in the brain. "Collectively, these results show that partial loss of SMS enhances autophagic flux, extends lifespan, and ameliorates neurodegenerative phenotypes in Tauopathy models." (PMID 38740758, 2024).
tumor (26 papers, 2015 to 2025). "Additionally, mRNA expression of spermine synthase in TNBC tumour tissue predicted poor overall survival and a higher risk of distant metastasis." (PMID 38187259, 2024). "Diacetyl spermine (DAS), a catabolic product of spermine mediated through tumour spermine synthase, was analysed in plasma in two articles." (PMID 38187259, 2024). "OAT, AGMAT, and SMS are only up-regulated in tumor tissue (Fig. 3a9, a12, a17, b6, b8, and b10), while ODC1 and SRM are highly expressed in tumor and lymphoid tissues (Fig. 3a13, a15, b7, and b9)." (PMID 37164975, 2023). "Compared to the control group, overexpression of SMS can promote tumor growth, while knockdown of SMS can significantly inhibit tumor formation and slow the rate of tumor growth." (PMID 36276112, 2022). "The bioinformatic data from the TCGA dataset provide a robust extension of our result, and confirm that SMS expression is beneficial to PDAC tumor growth and progression." (PMID 34945011, 2021). "Consistent with IHC staining results, SMS protein levels were elevated by almost twofold in tumor tissues compared with normal controls." (PMID 32591507, 2020). "Our work suggests that SMS overexpression is required to reduce spermidine level below the cytotoxic threshold and support tumor growth in CRC." (PMID 32591507, 2020). "Additionally, IHC analysis revealed that the protein levels of SMS were significantly higher in tumor tissues compared to NATs." (PMID 40963562, 2025). "SMS (spermine synthase) catalyzes the production of spermine from spermidine and is frequently upregulated in cancers, resulting in elevated polyamine level required for malignant transformation and tumor progression." (PMID 38057821, 2023). "In subtype analysis by tumor stage or cell differentiation status, we also did not detect significant association between SMS expression and CRC prognosis." (PMID 32591507, 2020). "Our data showed that genetic deletion of SMS causes a reprograming of polyamine metabolism with over-accumulation of spermidine, which sensitizes CRC cells to JQ1 as demonstrated by the synergistic induction of apoptosis and tumor regression." (PMID 32591507, 2020). "As such, overexpression of SMS, converting spermidine to spermine, is likely required to prevent the spermidine level from extending beyond the toxic threshold, and still maintain a relatively high level of spermidine favorable to support tumor growth." (PMID 32591507, 2020). "However, SMS deletion in combination with JQ1 treatment synergistically induced Bim expression and apoptosis associated with tumor regression." (PMID 32591507, 2020). "In contrast, upregulation of the biosynthetic activities of polyamine-producing enzymes such as ODC, SRM, SAMDC, and SMS by oncogenic signaling results in increased levels of polyamines, which are thought to play important roles in the maintenance of the transformed phenotype and tumor development." (PMID 32591507, 2020). "SMS inhibitors can significantly inhibit tumor cell growth, so SMS may be an oncogene." (PMID 32411183, 2020). "These SEs showed strong correlations with key genes involved in immunosuppression and tumor progression, including SPP1, RAC1, CTSC, and SMS." (PMID 40725473, 2025). "They found a significant increase in the expression of polyamine-related genes ODC1, SRM, SMS, SAT1, and spermine oxidase in tumour-affected tissues." (PMID 39408925, 2024). "The interference of the expression levels of SMS, P4HA1, PAH, PLOD2, and KYNU significantly decreased the invasion of tumor cells." (PMID 37511510, 2023). "The expression levels of SMS, ASNS, PLOD2, P4HA1, PAH, and KYNU were upregulated in tumor samples compared with normal samples, and the remaining three genes were downregulated." (PMID 37511510, 2023). "SMS was expressed in almost all cell types, including tumor cells, neurons, monocytes/macrophages, astrocytes, oligodendrocytes, and CD8 T cells, suggesting that SMS may affect TME." (PMID 40761256, 2025).
tumor (continued). "The results showed that both mRNA and protein of SMS were highly expressed in tumor tissues, while CPS1 was not significantly different in mRNA and protein levels." (PMID 37709932, 2023). "Bioinformatic analysis revealed miR-3613-3p might regulate cell cycle signaling pathway by targeting SMS, PAFAH1B2, or PDK3 to restrain tumor progression." (PMID 33494814, 2021). "It is reported that spermine synthase (SMS), in cooperation with MYC, can maintain CRC cell survival, so the combined inhibition of SMS and MYC signaling may be a promising strategy for inducing synergistic apoptosis and tumor regression." (PMID 33193630, 2020). "Combined inhibition of SMS and MYC signaling induces synergistic apoptosis and tumor regression." (PMID 32591507, 2020). "Additionally, miR-3613-3p might regulate cell cycle by targeting SMS, PAFAH1B2, or PDK3 to restrain tumor progression." (PMID 33494814, 2021). "In this study, we uncover an important function of SMS in cooperation with MYC to repress Bim expression through distinct regulatory pathways, and highlight the downregulation of Bim as a key survival signal downstream of oncogenic MYC and SMS signaling to facilitate CRC tumor growth." (PMID 32591507, 2020). "Interestingly, additional analysis of SMS expression in patients with stage I–IV CRC revealed that SMS expression was upregulated upon tumor initiation when compared with normal controls, but no further increase of SMS expression was observed as tumors progressed through stage II–IV." (PMID 32591507, 2020). "We found that transcripts for spermine synthase (Sms), which converts spermidine to spermine for final usage by the cell, were significantly more abundant in CD34− tumor cells from VE animals compared to non-VE controls." (PMID 25762633, 2015).
cancer (19 papers, 2008 to 2026). A tumor composed of atypical neoplastic, often pleomorphic cells that invade other tissues. "We also found the SRM, GAD1 and SMS were significantly elevated in contrast with those in paired normal samples in human cancers." (PMID 38637116, 2024). "There were also consistent trends in the mRNA and protein levels of SMS in pan-cancer tissues by analysis of the pan-cancer study cohorts of UALCAN." (PMID 36544774, 2022). "c-Myc on the other hand positively regulates ODC1 gene expression and along with spermine synthase promotes cancer cell survival." (PMID 34067619, 2021). "Taken together, we speculate that the high expression of SMS in HCC patients would cause spermine accumulation, which is confirmed in the urine and plasma of cancer patients." (PMID 36544774, 2022). "Multiple abnormalities in the control of polyamine metabolism and uptake may be responsible for increased levels of polyamines in cancer cells as compared to that of normal cells, and spermine synthase (SMS) is a member of the polyamine metabolic pathway." (PMID 32411183, 2020). "The roles of SMase and SMS in cancer treatment have been well recognized for decades." (PMID 27703266, 2016). "SMS gene is completely novel in this study with no known prior association with any type of cancer." (PMID 31417867, 2019). "In our initial analysis we noted increased expression of ODC1, spermidine synthase (SRM) spermine synthase (SMS) and decreased expression of SAT1 in cancers (n = 176) as compared to normal endometrial samples (n = 12)." (PMID 29240775, 2017). "Studies utilizing rMS or sMS as a treatment for conditions other than cancers, as well as those not considering these therapies as adjunctive therapy, were eliminated." (PMID 41898285, 2026). "For example, dysregulation of SMS may alter lipid metabolism, leading to changes in membrane composition that affect the localization and activity of MYO1B, thereby enhancing cancer cell motility and invasion." (PMID 38562924, 2024). "In our network models, it can be observed how histamine connects with polyamines metabolism through spermine synthase (SMS) and spermidine/spermine acetyl transferase (SAT1) and the cationic amino acid transporter (SLC7A1), which have been described previously in cancer cell models." (PMID 33799732, 2021). "Increased activity of enzymes catalysing pro-malignant sphingolipids formation reactions, such as glutamate-cysteine ligase (GCL), spermine synthase (SMS), sphingosine kinase (SphK) and ceramide kinase (CERK) results in the apoptosis escape and cancer progression." (PMID 32715369, 2020). "Our calculations showed that the altered SFA/MUFA ratio can affect the expression of some genes including HIGD2A and SMS suggesting that the changed FA ratio in EFA-CLA extract could be responsible, at least in part, for the specific response of the cancer cells." (PMID 27551323, 2016).
infection (6 papers, 2011 to 2025). The state of being infected such as from the introduction of a foreign agent such as serum, vaccine, antigenic substance or organism. "SMS deficiency significantly reduced both intracellular and extracellular JEV levels at 48 h after infection." (PMID 27892528, 2016). "In contrast, mutants in spermine synthase with low levels of spermine were less resistant to the same infection." (PMID 21869457, 2011). "Notably, spermidine levels show significant down-regulation in both early and late infection phases, while the expression of spermine synthase is significantly up-regulated in both periods." (PMID 38069062, 2023). "Notably, we also found a significant up-regulation of spermine synthase in the later stages of infection." (PMID 38069062, 2023). "Finally, A. thaliana overexpressing spermine synthase or wild-type exogenously supplied with spermine were shown to be more resistant to infection with Pseudomonas viridiflava." (PMID 21869457, 2011). "Meanwhile, the infection increased the mRNA transcription of MAT2A, AMD1, SMS, and AHCY mRNA with the same MOI." (PMID 38130504, 2024). "Consistently, an eight-fold increase in the expression of the spermine synthase (SMS) gene, which is responsible for producing of MTA from SAM, was observed during HIRRV infection in flounder HINAE cell." (PMID 37711614, 2023). "In this study, we focus on the role of SM and SMS in JEV attachment and infection of target cells using transformed mouse embryonic fibroblasts (tMEFs) derived from SMS knockout (KO) mice, which have depleted SM levels." (PMID 27892528, 2016). "In addition, induction of SMS1 but not SMS2 recovered JEV attachment and infection in SMS KO tMEFs." (PMID 27892528, 2016).
SMS also shares sentences with these, for which no sentence is quoted: genetic disorder (2 papers); lung carcinoma (2); prostate carcinoma (2); Bachmann-Bupp Syndrome (1); brain disorder (1); cutaneous leishmaniasis (1); developmental delay (1); endolymphatic hydrops (1); fungal infection (1); gastric cancer (1); Griscelli syndrome type 1 (1); head and neck squamous cell carcinoma (1); Kyphoscoliosis (1); laryngeal carcinoma (1); laryngeal squamous cell carcinoma (1); movement disorder (1); neurological diseases (1); Potocki-Lupski syndrome (1); progressive neurodegenerative disorder (1); prostate tumors (1); schizophrenia (1); Williams-Beuren syndrome (1); X-linked disease (1); X-linked intellectual disability (1).